MYC (MYC proto-oncogene, bHLH transcription factor)
Diseases named in the same sentence as MYC in open-access papers (continued):
Sharing a sentence is not in itself a finding about the gene and the disease.
medulloblastoma (continued). "Bioinformatic analysis of published datasets validated these pre-clinical findings, supporting a role for YB-1 in cell death and survival processes, cholesterol biosynthesis, response to therapeutics and MYC/mTOR signalling; as well as overall survival and metastasis in medulloblastoma patients." (PMID 36831428, 2023). "MYC-driven Group 3 medulloblastoma (MB) (subtype II) is a highly aggressive childhood brain tumor." (PMID 37783879, 2023). "Highly expressed PRMT5 stabilizes MYC and promotes its expression in medulloblastomas." (PMID 38136401, 2023). "Medulloblastoma, the most common malignant pediatric brain tumor, often harbors MYC amplifications." (PMID 36869047, 2023). "Further investigation to understand the mechanism of PRTM5–KLF4/KL5 interactions could uncover another new strategy to elucidate therapeutic targets for MYC-amplified medulloblastoma." (PMID 38136401, 2023). "This review explores the current knowledge of the effectiveness of PRMT5 inhibitors in preclinical and preliminary clinical settings, which may aid in understanding how to treat MYC-amplified medulloblastoma more effectively and safely." (PMID 38136401, 2023). "Furthermore, targeting PLK1, SETD8, and facilitator of chromatin transcription (FACT) with their respective inhibitors onvasertib, UNC0379, and CBL0137 has also shown preclinical activity against MYC-amplified medulloblastoma." (PMID 37568705, 2023). "Thus, although proliferation in both Group 3 medulloblastoma cell lines is driven by MYC amplification, the relative importance of co-amplified genes and cis-regulatory elements is specific to the genomic architecture of the amplicon." (PMID 37945900, 2023). "PRMT5 regulates oncogenes, including MYC, that are often deregulated in medulloblastomas." (PMID 38136401, 2023). "Likewise, the CDK1/5 inhibitor, alsterpaullone, has also shown significant inhibition of the MYC-dependent proliferation of against group 3 medulloblastoma cells." (PMID 37568705, 2023). "Moreover, we examined brains and spines for leptomeningeal dissemination, which is detected in around 40% of human Group 3 MB and has also been recapitulated in other MYC-driven medulloblastoma models." (PMID 37919824, 2023). "Consequently, PRKDC inhibitors were investigated for their potential role in therapy, and they were found to elicit radiosensitizing effects in the D458 cell line, which resembles group 3 medulloblastoma with MYC amplification." (PMID 37568705, 2023). "Proline was also increased in MYC-amplified medulloblastoma compared to normal brain." (PMID 35267619, 2022). "Several groups have reported promising findings of BET inhibition in MYC-amplified medulloblastoma." (PMID 35745584, 2022). "As MYC, another oncogene is also overexpressed in Group 3 medulloblastoma, OTX2 may promote tumorigenesis by cooperatively binding with MYC to target genes." (PMID 35546872, 2022). "In conclusion, high MYC medulloblastoma cells have different metabolic profiles in vitro compared to in vivo, and key vulnerabilities may be missed by not performing in vivo metabolic analyses." (PMID 35267619, 2022). "We detected significantly higher glucose-derived glutathione in tumors compared to normal brain, indicating that MYC-amplified medulloblastoma was using carbons from glucose to synthesize glutamate, which was then being incorporated into glutathione and glutamine." (PMID 35267619, 2022). "Additionally, CBL0137-induced SSRP1 chromatin trapping has been shown to downregulate DNA repair pathway in MYC-high medulloblastoma cells." (PMID 36539830, 2022). "In addition, MYC gene amplifications, such as in children with group 3 MYCC/MYCN-amplified medulloblastoma tumors, predispose patients to relapse and poor survival." (PMID 36540431, 2022). "However, we believe our report here is the first to describe the glutaminase II pathway as being predominant in MYC-amplified medulloblastoma." (PMID 35267619, 2022).
medulloblastoma (continued). "Genomic amplification of MYC defines a subset of poor-prognosis medulloblastoma." (PMID 35267619, 2022). "Orthotopic MYC-amplified medulloblastoma D425MED tumors had increased levels of glucosamine-6-phosphate compared to normal brain, suggesting increased reliance on the hexosamine biosynthetic pathway, which is the main pathway used for glycosylation of proteins." (PMID 35267619, 2022). "We also use only two human cell models of MYC-amplified medulloblastoma." (PMID 35267619, 2022). "Targeting these novel vulnerabilities may lead to improved outcomes in MYC-amplified medulloblastoma." (PMID 35267619, 2022). "Our observations may pave the way for pharmacologic manipulation of Acp2 as an approach of cerebellar developmental disorders such as the SHH group of medulloblastomas and Group 3 tumors and MYC signaling." (PMID 33804256, 2021). "In order to test whether a similar mechanism exists in c-MYC-driven medulloblastoma, we examined c-MYC protein levels in MB D458 cells treated with PLK1 inhibitors PCM-075 and BI6727." (PMID 33494392, 2021). "Moreover, studies targeting histone de-acetylases (HDACs) have revealed growth inhibition of MYC-driven medulloblastomas." (PMID 34922631, 2021). "Group 3 medulloblastoma (MB) is often accompanied by MYC amplification and has a poor prognosis." (PMID 33494392, 2021). "Their use in combination with CDK2 inhibitor is being studied in MYC-driven medulloblastoma." (PMID 34638300, 2021). "However, aberrations in RB1 and MYC/MYCN as well as leptomeningeal dissemination are characteristics of embryonal tumors as medulloblastomas or atypical teratoid rhabdoid tumors." (PMID 33876327, 2021). "Therefore, miR-193a mediated decrease in the activity of MYC is likely to contribute to the miR-193a mediated widespread repression of gene expression in the MYC overexpressing Group 3 medulloblastoma cells." (PMID 32410663, 2020). "Therefore, miR-193a has therapeutic potential in the treatment of not only Group 3 medulloblastomas but possibly other MYC overexpressing aggressive cancers as well." (PMID 32410663, 2020). "Thus, miR-193a countered the transcription amplifying effect of MYC resulting in the inhibition of growth and tumorigenic potential of the MYC amplified medulloblastoma cells." (PMID 32410663, 2020). "We couldn’t obtain any publicly available ChIP-Seq data of MYC, to check the MYC dependent regulation possibility in Medulloblastoma." (PMID 31932624, 2020). "We also showed that MYC amplification, the hallmark driver event detected in 12–17% of Group 3 medulloblastomas, was absent in adult Group 3 tumours." (PMID 33172502, 2020). "MiR-193a could be effective for the treatment of not only Group 3 medulloblastomas but possibly other MYC overexpressing aggressive cancers as well." (PMID 32410663, 2020). "Further investigation of targeting unexplored PRMT5-KLF4 interactions in medulloblastoma might be another new strategy to develop therapy for MYC-driven medulloblastoma." (PMID 31694585, 2019). "MYC amplification is a known marker for poor prognosis in the Group 3 medulloblastomas." (PMID 30944042, 2019).
medulloblastoma (continued). "Therefore, our data provide insights about the mechanisms underlying BETi effects and the appearance of resistance and support the therapeutic use of combined cell-cycle inhibitors with BETi in MYC-amplified medulloblastoma." (PMID 31160565, 2019). "Mechanistic studies revealed that PRMT5 could elevate MYC expression and stability, enhancing medulloblastoma tumorigenicity." (PMID 31694585, 2019). "For example, transcription factors of the MYC family (c-MYC and MYCN), which are associated with aggressive pediatric cancers such as medulloblastoma and neuroblastoma, bind to and activate the TERT promoter, resulting in high TERT mRNA levels of MYC- and MYCN-amplified tumors." (PMID 31757062, 2019). "PRMT5 and MYC expression are positively correlated in medulloblastoma cells." (PMID 31694585, 2019). "BET-bromodomain inhibition (BETi) has shown pre-clinical promise for MYC-amplified medulloblastoma." (PMID 31160565, 2019). "Here, we showed that PRMT5 is a novel regulator of MYC protein in medulloblastoma." (PMID 31694585, 2019). "Based on these observations, we hypothesized that PRMT5 is a novel regulator of MYC expression whose inhibition may serve as a novel therapeutic strategy in MYC-driven medulloblastoma." (PMID 31694585, 2019). "To confirm whether endogenous PRMT5 physically interacts with MYC protein in medulloblastoma, we performed a co-immunoprecipitation experiment in MYC-driven HD-MB-03 medulloblastoma cells using MYC and PRMT5 antibodies." (PMID 31694585, 2019). "NOTCH1-silenced medulloblastoma cells express lower levels of MYC." (PMID 30297829, 2018). "Indeed, one recently published paper demonstrated that only a combined treatment with pan class I/II HDACIs (e.g., LBH‐589) and PI3Ki (BKM‐120) can effectively inhibit the growth of aggressive MYC‐driven medulloblastoma in mice." (PMID 29523594, 2018). "Additional studies have led to the identification of an additional medulloblastoma subgroup characterized by c-MYC gene copy number gains and transcriptionally by enrichment of photoreceptor pathways; this molecular subgroup is associated with low rates of event-free and overall survival." (PMID 30279357, 2018). "In this context we documented previously that the clinically available highly specific PI3K inhibitor GDC-0941 displays profound in vitro activity and prolonged the life of tumor-bearing animals in an orthotopic xenograft mouse model of most aggressive MYC-amplified human medulloblastoma." (PMID 28159923, 2017). "In summary, we describe a novel orthotopic MYC-driven PDX model of Group 3 medulloblastoma." (PMID 28417956, 2017). "c-MYC is highly expressed in WNT tumors, which do not have c-MYC gene amplification, whereas Group 3 medulloblastomas are often associated with c-MYC amplification (~16%–17%) and the worst overall prognosis." (PMID 28333115, 2017). "Interestingly, the BBB is disrupted in certain types of WNT-driven medulloblastomas, a subgroup that generally expresses high levels of MYC." (PMID 28333115, 2017).
medulloblastoma (continued). "Furthermore, OTX2 has been shown to directly upregulate the expression of c-MYC in medulloblastoma via cis-regulatory elements in the MYC promoter region." (PMID 29124525, 2017). "As precision medicine becomes an ever-present theme, the efforts at institutional and cooperative group levels to establish patient-derived primary cell cultures and xenografts for MYC+ medulloblastoma patients may inform these efforts even further." (PMID 27255663, 2016). "Medulloblastoma has other potential therapeutic targets for non-MYC-driven tumors." (PMID 27382528, 2016). "Early studies identified specific miRNA expression patterns that could distinguish differing medulloblastoma molecular features, such as c-MYC overexpressing tumors, and may therefore provide interesting insights into the factors regulating tumorigenesis." (PMID 27775567, 2016). "In pediatric patients, “group 3” non-WNT/non-SHH medulloblastomas contain standard-risk medulloblastomas (not behaving differently from “group 4” patients) as well as MYC-amplified tumors showing mostly a very poor prognosis." (PMID 27781424, 2016). "MYC amplification is considered an important prognostic biomarker within the non-WNT/non-SHH medulloblastomas but not as a diagnostic marker defining an own entity." (PMID 27781424, 2016). "One of the key regulatory kinases involved in multiple stages of mitosis is Aurora kinase B. We hypothesized that medulloblastoma cells that overexpress MYC would be uniquely sensitized to the apoptotic effects of Aurora B inhibition." (PMID 25739120, 2015). "Furthermore, ALP reverses the Group 3 medulloblastoma gene signature and downregulates many cell cycle-related genes, including MYC." (PMID 26061748, 2015). "MYC overexpression sensitized medulloblastoma cells to cell death upon Aurora B inhibition." (PMID 25739120, 2015). "After the identification of useful high-risk markers such as MYC amplification, or low-risk markers such as the WNT-driven subgroup, we aimed to further substratify the large remaining group of “intermediate molecular risk” medulloblastoma." (PMID 24791927, 2014). "Wnt medulloblastomas also have high levels of expression of MYC." (PMID 25101241, 2014). "Pursuing the rational that JQ1 would broadly affect other MYC driven tumors we tested this hypothesis on a panel of medulloblastoma cells." (PMID 24796395, 2014). "Moreover treatment with JQ1 significantly attenuated long-term anchorage independent growth of multiple MYC driven medulloblastoma cell lines (p < 0.005)." (PMID 24796395, 2014). "Importantly the c-MYC oncogene family is the most commonly amplified gene set in medulloblastoma further emphasizing the need to target these tumors." (PMID 24796395, 2014). "Pharmacologically inhibiting MYC expression may, thus, have clinical utility given its pathogenetic role in medulloblastoma." (PMID 24231268, 2013). "As high-level MYC expression may drive the most aggressive characteristic of medulloblastomas, targeted inhibition of MYC should have clinical utility." (PMID 24231268, 2013). "Experimentally, high MYC expression induces metastatic tumors in orthotopic medulloblastoma models." (PMID 23768125, 2013). "The meta-analysis data also show that prognostic factors like metastatic stage, histology, MYC and MYCN amplifications, 10q loss, 17p loss, and 17q gain, previously reported for medulloblastoma as a single disease, remain prognostic in these combined series of all patients." (PMID 22358457, 2012). "Likewise, MYC and mTOR signaling activation has been demonstrated to synergize together in cancer biology, directing tumor deterioration and drug resistance in several malignancies, including medulloblastoma." (PMID 39779613, 2025).
medulloblastoma (continued). "Indeed, our previous studies demonstrate that the key components of protein synthesis machinery, including mTOR signaling and MYC targets, are overexpressed and activated in MYC-amplified medulloblastoma, confirming MYC-dependent addiction of enhanced protein synthesis in medulloblastoma." (PMID 39779613, 2025). "Thus, inhibiting enhanced protein synthesis by targeting the MYC indirectly and mTOR pathways together may present a highly appropriate strategy for treating MYC-driven medulloblastoma and other MYC-addicted cancers." (PMID 39779613, 2025). "Ribavirin could be a valuable addition for MYC-amplified medulloblastoma targeted to eIF4E." (PMID 39779613, 2025). "The exact MYC oncogenic programs regulated by PRMT5 in medulloblastoma are largely unknown." (PMID 38136401, 2023). "Indeed, the α5-GABAA-specific agonist, QHii066, was able to induce apoptosis and cell cycle arrest of MYC-amplified medulloblastoma cells and to sensitize mice harboring D425 tumors, which mimic group 3 medulloblastoma with MYC amplification, to radiation therapy and cisplatin." (PMID 37568705, 2023). "Along these lines, it appears reasonable that IGF2BP1 supports MYC/N-driven proliferation capacity in embryonal neuroblasts, other childhood/youth cancers with strong MYC/N-dependency and aberration at Chr 17q, e.g. rhabdomyosarcoma and medulloblastoma, as well as carcinomas in general." (PMID 37246217, 2023). "In addition to i-SOX2-LNCaP and i-SOX2-ONS76, characterization of three additional engineered i-SOX2 tumor cell lines indicated that elevating SOX2 decreases MYC mRNA and protein in five tumor cell lines representing three human cancer types (prostate, medulloblastoma, and colorectal)." (PMID 35454854, 2022). "Importantly, PVT1, a non-coding oncogene, neighbors the MYC oncogene, with both genes known to be amplified in cancer, and the medulloblastoma samples harboring the observed PVT1 fusions belong to the Group 3 medulloblastoma subtype, characterized by MYC amplifications." (PMID 35804907, 2022). "We hypothesized that due to alterations in oxygen tension, nutrient availability and the microenvironment there would be significant discrepancies between the metabolic profile of the same MYC-amplified medulloblastoma cells in vitro, in flank tumors and in orthotopic tumors." (PMID 35267619, 2022). "Therefore, we sought to investigate methods that may improve treatment outcomes for high-risk medulloblastoma patients by preclinically evaluating the radiosensitizing potential of PARP inhibition in MYC-amplified Group 3 medulloblastoma models." (PMID 33996894, 2021). "However, ectopic expression of either human c-MYC or MYCN (mutationally stabilized and wild-type) in conjunction with SHH expression in Nestin-expression progenitor cells generated SHH medulloblastoma at a significantly increased incidence compared with infection with RCAS-SHH alone." (PMID 28333115, 2017). "Moreover, MYC–MIZ-1 complexes have been shown to repress genes important for neuronal differentiation in MYC-dependent Group 3 medulloblastoma, thus allowing tumor cells to retain a stem-like state, so targeting this complex would also be of therapeutic interest." (PMID 28333115, 2017). "Moreover, OTX2 and c-MYC are frequently coexpressed at high levels in medulloblastoma and regulate many of the same genes, indicating there might be a functional interaction between these two genes." (PMID 27775567, 2016). "Due to the limited success in developing small molecule inhibitors of MYC, targeting important cellular processes, such as the cell cycle, may prove to be a viable therapeutic strategy in MYC-dependent tumors, including Group 3 medulloblastomas." (PMID 26061748, 2015).